NLRP3 (NLR family pyrin domain containing 3)
Diseases named in the same sentence as NLRP3 in open-access papers (continued):
Sharing a sentence is not in itself a finding about the gene and the disease.
Myocardial fibrosis (continued). "It achieved its anti-inflammatory and antioxidant effects by regulating the SIRT1/NF-κB/NLRP3 inflammasome signaling pathway, thereby reducing myocardial fibrosis and hypertrophy." (PMID 39925805, 2025). "In pressure overload-induced HF, the activation of the NLRP3 inflammasome was identified as a critical factor driving the progression of myocardial fibrosis." (PMID 39925805, 2025). "Taken together, IL-1β functions as a factor downstream of NLRP3 inflammatory vesicles and participates in the process of myocardial fibrosis by promoting the production of factors such as TGF-β1 and activating FGF-2 to promote End-MT." (PMID 40881586, 2025). "Urea directly activates NLRP3 inflammatory vesicles and stimulates monocytes to secrete IL-1β, driving coronary artery calcification and myocardial fibrosis." (PMID 40937404, 2025). "Inflammatory responses can not only activate multiple inflammatory cells, inflammatory factors, and inflammatory pathways, but also have profound effects on myocardial fibrosis through pathways such as NLRP3 inflammatory vesicles." (PMID 40881586, 2025). "And the overexpression of GAS5 inhibited the myocardial fibrosis and the NLRP3 inflammasome activation." (PMID 38561456, 2024). "Impeding NLRP3 inflammasome reduced cardiac lipid accumulation and attenuated cardiac hypertrophy and myocardial fibrosis." (PMID 39604027, 2024). "The results showed that mir-217 negatively regulated SIRT1 and aggravated the myocardial fibrosis induced by TGF-β1 via NLRP3 inflammasome activation." (PMID 38561456, 2024). "AS-IV (200 mg/kg/day) alleviated isoproterenol-induced cardiac fibrosis in BALB/c mice by inhibiting the NLRP3 inflammasome pathway, indicating that AS-IV improves myocardial fibrosis by inhibiting inflammation." (PMID 37251311, 2023). "In this work, we confirmed that chicoric acid inhibits isoproterenol‐induced myocardial fibrosis by regulating the HK1/NLRP3 inflammasome pathway, thereby inhibiting inflammation, oxidative stress, and apoptosis." (PMID 38268894, 2023). "In a mouse model of HF with transverse aortic constriction (TAC), the content of NLRP3 increased and the degree of myocardial fibrosis increased." (PMID 35509275, 2022). "To further confirm the role of NLRP3 inflammasome in glucose fluctuation-mediated myocardial fibrosis, we used siRNA to inhibit the expression of NLRP3 in NRCFs." (PMID 35592403, 2022). "Metformin inhibited the activation of TNF-α, IL-6, IL-1β, and NLRP3 inflammasome, reduced the size of MI and myocardial fibrosis, enhanced the activity of myocardial cells, reduced the activity of LDH, inhibited pyroptosis and inflammation." (PMID 35509275, 2022). "Pirfenidone can regulate the ROS-dependent NLRP3-IL-1β signaling pathway by inhibiting NLRP3, improving left ventricular hypertrophy and myocardial fibrosis in rats with TAC." (PMID 35509275, 2022). "The results showed that didymin can improve myocardial dysfunction after I/R, inhibit myocardial fibrosis, apoptosis, inflammation and NLRP3 activation." (PMID 36416076, 2022). "We demonstrated that LQF can efficiently inhibit TLR4/MyD88/NF-κB signaling pathway activation and thereby inhibit NLRP3 inflammasome activation and alleviate myocardial fibrosis in MI mice." (PMID 35310035, 2022). "At the same time, in vivo experiments confirmed that GN can well improve myocardial fibrosis and cardiac function and inhibit the activation of NLRP3 inflammasomes and the formation of myocardial collagen deposition." (PMID 35401934, 2022). "A recent study revealed that MCC950, a specific inhibitor of the NLRP3 inflammasome, can attenuate myocardial fibrosis and improve cardiac remodeling in a mouse model of MI." (PMID 36140279, 2022). "In summary, our research suggests that blood glucose fluctuations can aggravate NLRP3 inflammasome-induced myocardial fibrosis by activating NF-κB." (PMID 35592403, 2022).
Myocardial fibrosis (continued). "In the past decade, NLRP3 inflammasome has been demonstrated to be widely involved in myocardial fibrosis." (PMID 35310035, 2022). "The covalent NLRP3 inflammasome inhibitor oridonin reduces expression levels of NLRP3, IL-1β, IL-18, and myocardial fibrosis and preserves cardiac function in a mouse MI model." (PMID 35273164, 2022). "Our results suggest that Calhex231 ameliorates myocardial fibrosis post MI in rats, likely through inhibiting autophagy‐NLRP3 inflammasome pathway in macrophages." (PMID 33043596, 2020). "Pirfenidone improved TAC-induced left ventricular hypertrophy and myocardial fibrosis in a mouse model through inhibiting NLRP3 inflammasome assembly, and regulating the NLRP3-IL-1β signaling pathway in both the ROS-dependent and ROS-independent pathways." (PMID 31354731, 2019). "We critically examine how loss-of-function mutations in epigenetic regulators promote a pro-inflammatory macrophage phenotype through NLRP3 inflammasome activation and IL-1β/IL-6 signaling, thereby accelerating atherogenesis, plaque instability, and myocardial fibrosis." (PMID 42039360, 2026). "Importantly, the degree of NLRP3 inflammasome activation is positively correlated with the severity of myocardial fibrosis." (PMID 39925805, 2025). "Advanced glycation end products (AGEs) activate the NF-κB pathway via the RAGE receptor, leading to the release of TNF-α, IL-6, and IL-1β, while excessive mitochondrial ROS generation further activates the NLRP3 inflammasome, exacerbating myocardial fibrosis and apoptosis." (PMID 40520009, 2025). "In summary, NLRP3 inflammatory vesicles affect the development of myocardial fibrosis mainly through three pathways: cleavage and release of mature inflammatory factors, activation of inflammation-related pathways, and activation of sterile inflammatory responses." (PMID 40881586, 2025). "And mir-217 could down-regulate the expression of SIRT1 then aggravate myocardial fibrosis induced by NLRP3 inflammasome activation-mediated pyroptosis in vitro." (PMID 38561456, 2024). "Our study has shown that by reducing the expression of these proteins, treatment with PF can mitigate the left ventricular remodeling induced by AMI under persistent hypobaric hypoxia by counteracting inflammation, myocardial fibrosis, and apoptosis triggered by the NLRP3 inflammasome." (PMID 38427210, 2024). "Blockade of either NLRP3 or IL-18 additionally reduced production of chemokines that attract monocytes, lowered expression of IL-6, with blunted proinflammatory macrophage infiltration and ameliorated myocardial fibrosis." (PMID 38093747, 2023). "Likewise, in situations of pressure overload–mediated cardiac damage, ROS and NF-κB stimulated NLRP3 inflammasome activation leading to increased IL-1 and IL-18 production and increased inflammatory monocyte infiltration and myocardial fibrosis." (PMID 38093747, 2023). "In addition, the role of NLRP3 inflammasome in the progression of myocardial fibrosis has also been demonstrated in in vitro and in vivo studies." (PMID 36140279, 2022). "In conclusion, LQF may downregulate TLR4/MyD88/NF-κB pathway and inhibit the activation of NLRP3 inflammasome, thereby reducing inflammatory response and myocardial fibrosis." (PMID 35310035, 2022). "Our results illustrated that the inhibition of NLRP3 reversed myocardial fibrosis." (PMID 35592403, 2022). "Hence, it is reasonable to suggest that targeting these pro-fibrotic factors with CTGF, TGF-β, RAAS, Gal-3, NLRP3, and βAR inhibitors can be a promising approach for the treatment of myocardial fibrosis after cardiac tissue damage/remodeling." (PMID 36140279, 2022). "In vivo experimental results showed that LGZGD could significantly improve cardiac function, alleviate myocardial fibrosis, reduce the level of inflammatory factors, and inhibit the activation of NLRP3/Caspase-1/GSDMD signaling pathway." (PMID 35615687, 2022).
Myocardial fibrosis (continued). "It is well known that the NLRP3 inflammasome is extensively involved in myocardial fibrosis." (PMID 35310035, 2022). "The NLRP3 inflammasome partially induces myocardial fibrosis and cardiac dysfunction." (PMID 35379787, 2022). "Collectively, we demonstrated that NLRP3 inflammasome was activated after exposure to glucose fluctuations and may be responsible for promoting myocardial fibrosis." (PMID 35592403, 2022). "In this study, MI rats and peritoneal macrophages were treated with Calhex231, CaSR agonist, autophagy agonist, and antagonist or the inhibitor of NLRP3 inflammasome in order to elucidate the role and molecular mechanism of Calhex231 in myocardial fibrosis post MI." (PMID 33043596, 2020). "Thus, our data indicate that MLK3 leads to myocardial fibrosis and cardiac dysfunction through NF-κB/NLRP3-mediated inflammation and pyroptosis in the early stage of pressure overload." (PMID 32710001, 2020). "Our study indicated that Calhex231 improved cardiac function and ameliorated myocardial fibrosis post MI, likely via the inhibition of autophagy‐mediated NLRP3 inflammasome activation; this provides a new therapeutic target for ventricular remodelling‐related cardiovascular diseases." (PMID 33043596, 2020). "It is established that NLR family pyrin domain containing 3 (NLRP3) inflammasome activation were associated with increased inflammatory mediators and profibrotic factor production, resulting in myocardial fibrosis, cardiomyocyte hypertrophy and impaired cardiac function." (PMID 30940158, 2019). "Concurrently, EMPA treatment effectively suppressed activation of the NF-κB/NLRP3 signaling pathway, accompanied by reduced levels of IL-1β and IL-18, suggesting decreased levels of cardiomyocyte pyroptosis and markedly alleviated inflammatory infiltration and myocardial fibrosis." (PMID 42099788, 2026). "Similarly, in STZ‐induced diabetic model rats and high glucose‐induced H9C2 cells, NLRP3 and IL‐1β expression were significantly increased compared to controls, whereas activation of the NLRP3 pathway modulated cardiomyocyte pyroptosis and improved myocardial fibrosis and cardiac function in DCM." (PMID 41276460, 2025). "Inhibition of NLRP3 has been shown to effectively delay the progression of myocardial fibrosis, suggesting that targeting NLRP3 could be a novel therapeutic approach for treating myocardial fibrosis." (PMID 39223947, 2024). "Enhanced activation of NLRP3-inflammasome in AMs increases caspase-1 cleavage and caspase-1-mediated apoptosis, releases inflammatory cytokines, recruits macrophages and other immune cells, and induces myocardial fibrosis and promotes the formation of AF maintenance substrates." (PMID 38077349, 2023). "Moreover, TP could prevent IgAN progression and improve myocardial fibrosis by down-regulating NLRP3 inflammasomes." (PMID 36938748, 2023). "Thus, we demonstrated that activation of NF-κB in response to glucose fluctuations could promote NLRP3 inflammasome assembling and aggravate myocardial fibrosis." (PMID 35592403, 2022). "Therefore, to clarify whether the effect of LQF in reducing myocardial fibrosis is related to inhibited NLRP3 inflammasome, next, we observed the expression of NLRP3 inflammasome in myocardial tissue of MI mice." (PMID 35310035, 2022). "Mechanistically, tretinoin impeded the TGF-β1/Smad3 pathway by dampening the activation of the NLRP3 inflammasome, which in turn attenuated TAC-induced myocardial fibrosis and hypertrophy and improved cardiac function." (PMID 39925805, 2025). "Second, NLRP3 inflammatory vesicles activate the TGF-β/Smad and MAPK signaling pathways, which in turn lead to myocardial fibrosis through various pathways, including the promotion of inflammatory factor recruitment." (PMID 40881586, 2025).
Myocardial fibrosis (continued). "In summary, the mechanism of QL treat of myocardial fibrosis is mainly related to the down-regulation of TGF-β1/Smad3, in which inflammatory mediators like NLRP3, miR-133a and miR-345-3p play an important role." (PMID 40881586, 2025). "Mechanistically, it inhibited NLRP3 inflammasome activation by upregulating SIRT1 expression, thereby reducing cardiac inflammatory infiltration, myocardial fibrosis, and cardiomyocyte apoptosis, ultimately mitigating DOX-induced cardiac injury." (PMID 39925805, 2025). "By inhibiting the NLRP3 inflammasome, it reduced the expression of fibrosis markers, including collagen-I, collagen-III, collagen-IV, and α-SMA, thereby alleviating myocardial fibrosis and cardiac dysfunction following MI." (PMID 39925805, 2025). "Monocyte activation, IL-6, TNF-α production, and NLRP3 inflammasome activation are heightened in CRS, contributing to vascular and myocardial fibrosis." (PMID 40806569, 2025). "In addition, astragaloside IV (AS-IV), the Astragalus membranaceus major bioactive component, was able to reduce myocardial fibrosis and myocardial hypertrophy, which may be attributed to decreased ROS levels and the suppression of the NLRP3/Caspase-1/GSDMD pyroptosis pathway after AS-IV treatment." (PMID 39940319, 2025). "In pharmacological intervention experiments, selective blockade with the P2X7 antagonist A438079 or the NLRP3 inhibitor MCC950 improved diastolic function and exercise capacity and attenuated myocardial fibrosis and cardiomyocyte hypertrophy." (PMID 40958035, 2025). "In summary, QSYQ inhibits NLRP3 inflammatory vesicles and inflammatory signaling pathways such as TGFβ1/Smads, STAT3, and NF-κB, and has multi-target anti-myocardial fibrosis properties." (PMID 40881586, 2025). "Polygonatum has also been shown to attenuate myocardial fibrosis and inflammation and restore the morphology and function of myocardial tissue by regulating AMPK-Nrf2, NF-κB, TGF-β1/Smads, and NLRP3 inflammasome signaling pathway." (PMID 38163901, 2024). "Our data indicated that the inhibition of NF-κB/p65 nucleation reduced NLRP3 expression and NLRP3-ASC interaction, leading to reverse the effects of myocardial fibrosis induced by glucose fluctuations." (PMID 35592403, 2022). "In vivo, NLRP3 inhibition with MCC950 reversed left ventricular systolic dysfunction and myocardial fibrosis induced by glucose fluctuations." (PMID 35592403, 2022). "Therefore, NLRP3 inflammasome may be a potential target for the treatment of myocardial fibrosis." (PMID 35310035, 2022). "Together, these findings in the present study indicate that LQF alleviated myocardial fibrosis owing to inhibiting TLR4/MyD88/NF-κB signaling pathway and inhibited NLRP3 inflammasome activation." (PMID 35310035, 2022). "After 2 weeks of treatment with NLRP3 inflammasome inhibitor MCC950 in MI/R mice, myocardial fibrosis and NLRP3-induced pyroptosis were significantly reduced." (PMID 35615687, 2022). "In summary, BYHWD exerts anti-inflammatory effects by down-regulating the expression of inflammatory factors such as IL-6, IL-1β, IL-18, and NLRP3, and inhibiting the JAK/STAT and TLR4/NF-κB signaling pathways, thereby slowing down the process of myocardial fibrosis." (PMID 40881586, 2025). "Recent studies have shown that inhibiting the activation of NLRP3 inflammasome in macrophages improved angiotensin II (Ang II)-induced myocardial remodeling and myocardial fibrosis, but macrophage polarization during this process was not investigated." (PMID 38715976, 2024). "Moreover, LQF group inhibited the protein expressions of NLRP3, ASC, and cleaved caspase-1; these data supported the notion that LQF alleviates myocardial fibrosis by inhibiting the activation of NLRP3 inflammasome." (PMID 35310035, 2022). "In addition, we showed that TMAO promoted myocardial fibrosis via TGF-β signaling in vitro and in vivo and that the activation of the NLRP3 inflammasome played a crucial role in TMAO-induced cardiac fibrosis." (PMID 31354519, 2019).
Myocardial fibrosis (continued). "QSYQ inhibited the TGFβ1/Smads signaling pathway and NLRP3 inflammatory vesicle expression, and significantly suppressed monocyte infiltration and macrophage polarization toward M2, thereby inhibiting MMP-2 and MMP-9 expression and ameliorating I/R induced myocardial fibrosis." (PMID 40881586, 2025). "BYHWD down-regulated IL-18, NLRP3 inflammatory vesicles, and TLR4/NF-κB signaling pathway by inhibiting the TLR4 signaling pathway, and suppressed the expression level of collagen I/III, thereby attenuating cardiac inflammation and myocardial fibrosis after myocardial infarction." (PMID 40881586, 2025). "The levels of the NLRP3 inflammasome were notably increased in mice with TAC and were involved in the increase in inflammatory mediators and profibrotic factor production, leading to myocardial fibrosis, cardiomyocyte hypertrophy, and impaired cardiac function." (PMID 31354731, 2019).